ZNF212 (zinc finger protein 212)
Description:
May be involved in transcriptional regulation.
Synonyms: ZNFC150; C2H2-150; ZNF182
Tractability: PROTAC: ubiquitination databases record sites on it.
Gene: Protein-coding gene on chromosome 7 (149,239,651 to 149,255,956, forward strand). Ensembl gene ENSG00000170260.
Subcellular location: Nucleus
Subcellular location (Human Protein Atlas): Nucleoplasm
Pathways (Reactome):
Gene expression (Transcription): Generic Transcription Pathway
Gene Ontology:
Molecular function: DNA-binding transcription activator activity, RNA polymerase II-specific; identical protein binding; protein binding; DNA-binding transcription factor activity; RNA polymerase II cis-regulatory region sequence-specific DNA binding; zinc ion binding
Biological process: neuron apoptotic process; positive regulation of transcription by RNA polymerase II; walking behavior; regulation of DNA-templated transcription; regulation of transcription by RNA polymerase II
Cellular component: nucleoplasm; nucleus
Genetic constraint (gnomAD): Loss-of-function variants: 32 observed, 47.44 expected, observed/expected ratio (o/e) 0.67, 90% interval 0.51 to 0.91. The upper end of that interval is the gene's LOEUF score, 0.91, which puts it in group 3 of 6, group 1 being the genes least tolerant of losing a copy. Missense variants: 555 observed, 648.54 expected, observed/expected ratio (o/e) 0.86, 90% interval 0.8 to 0.92. Synonymous variants: 242 observed, 260.34 expected, observed/expected ratio (o/e) 0.93, 90% interval 0.84 to 1.03.
Homologues: Orthologues: chimpanzee ZNF212 (98% identical), rabbit ZNF212 (90% identical), pig ZNF212 (81% identical), guinea pig ZNF212 (81% identical), mouse Zfp212 (79% identical), rat Zfp212 (79% identical), Drosophila melanogaster CG10631 (21% identical), Drosophila melanogaster CG11902 (15% identical), zebrafish znf574 (15% identical), Drosophila melanogaster CG11696 (9% identical). Paralogues in human: ZNF783 (43% identical), ZNF366 (16% identical), ZNF865 (15% identical), ZNF667 (15% identical), ZNF710 (15% identical), ZNF671 (13% identical), ZNF662 (12% identical).
Diseases named in the same sentence as ZNF212 in open-access papers:
ZNF212 is named in the same sentence as 4 diseases in open-access papers, as found by Europe PMC text mining. Sharing a sentence is not in itself a finding about the gene and the disease. The quoted sentences say what the papers report.
Ataxia (1 paper, 2021). Ataxia refers to impaired coordination of voluntary muscle movement. "To identify the target genes of ZNF212 associated with the behavioral phenotype of Zfp212-KO mice, we selected 39 ataxia-related genes and monitored their mRNA levels in the Cb of 8-week-old Zfp212-WT and KO mice." (PMID 34815492, 2021). "Notably, significant downregulation of Zfp212 and PLD3 was observed in the Cb of alcohol-induced ataxia mice, suggesting that ZNF212 is an essential protein that maintains Purkinje cell health and regulates the level of PLD3 in the Cb." (PMID 34815492, 2021).
colorectal cancer (1 paper, 2023). A primary or metastatic malignant neoplasm that affects the colon or rectum. "For example, ZNF212 and ZNF367 can regulate the apoptosis of ovarian tumour cells and the proliferation of colorectal cancer cells, respectively." (PMID 36803542, 2023).
Fanconi anemia (1 paper, 2023). Fanconi anemia (FA) is a hereditary DNA repair disorder characterized by progressive pancytopenia with bone marrow failure, variable congenital malformations and predisposition to develop hematological or solid tumors. "In ICL repair, Zfp212, the mouse homolog of ZNF212, appears to act upstream Neil3 and Fanconi anemia (FA) pathways in the same way as Traip does." (PMID 36594163, 2023). "In addition, an epistatic analysis of Zfp212, the mouse homolog of human ZNF212, in mouse embryonic stem cells (mESCs), shows that it appears to act upstream of both the Neil3 and Fanconi anemia (FA) pathways of ICLs repair." (PMID 36594163, 2023).
ZNF212 also shares sentences with these, for which no sentence is quoted: ovarian tumour (1 paper).